TMEM94 (transmembrane protein 94)
Description:
Could function in the uptake of Mg(2+) from the cytosol into the endoplasmic reticulum and regulate intracellular Mg(2+) homeostasis.
Synonyms: ERMA; KIAA0195; IDDCDF
Tractability: Antibody: UniProt predicts a signal peptide or a membrane-spanning region. PROTAC: ubiquitination databases record sites on it; its protein half-life has been measured.
Gene: Protein-coding gene on chromosome 17 (75,441,159 to 75,500,452, forward strand). Ensembl gene ENSG00000177728.
Subcellular location: Endoplasmic reticulum membrane
Subcellular location (Human Protein Atlas): Nucleoplasm; Nuclear bodies
Gene Ontology:
Molecular function: P-type magnesium transporter activity
Biological process: magnesium ion transport from cytosol to endoplasmic reticulum; intracellular magnesium ion homeostasis
Cellular component: endoplasmic reticulum membrane; nucleoplasm
Genetic constraint (gnomAD): Loss-of-function variants: 81 observed, 162.26 expected, observed/expected ratio (o/e) 0.5, 90% interval 0.42 to 0.6. The upper end of that interval is the gene's LOEUF score, 0.6, which puts it in group 2 of 6, group 1 being the genes least tolerant of losing a copy. Missense variants: 1,435 observed, 1,817.2 expected, observed/expected ratio (o/e) 0.79, 90% interval 0.75 to 0.82. Synonymous variants: 751 observed, 757.98 expected, observed/expected ratio (o/e) 0.99, 90% interval 0.93 to 1.05.
Gene-disease validity (ClinGen):
ClinGen rates the evidence that TMEM94 causes each of these diseases.
intellectual developmental disorder with cardiac defects and dysmorphic facies (autosomal recessive): Definitive.
Homologues: Orthologues: chimpanzee TMEM94 (99% identical), macaque TMEM94 (99% identical), dog TMEM94 (96% identical), mouse Tmem94 (96% identical), rat Tmem94 (95% identical), guinea pig TMEM94 (94% identical), rabbit TMEM94 (94% identical), pig TMEM94 (94% identical), tropical clawed frog tmem94 (70% identical), zebrafish tmem94 (68% identical), Drosophila melanogaster l(2)k05819 (33% identical), Caenorhabditis elegans D1007.15 (25% identical).
Diseases named in the same sentence as TMEM94 in open-access papers:
TMEM94 is named in the same sentence as 10 diseases in open-access papers, as found by Europe PMC text mining. Sharing a sentence is not in itself a finding about the gene and the disease. The quoted sentences say what the papers report.
congenital heart defects (1 paper, 2023). "Importantly, this enhancer region interacts with the distal promoter region of Transmembrane protein 94 (TMEM94), and biallelic TMEM94 truncating mutation is associated with congenital heart defects." (PMID 37283586, 2023).
TMEM94 also shares sentences with these, for which no sentence is quoted: Sepsis (2 papers); acne (1); bacterial infections (1); campylobacteriosis (1); cholera (1); infection (1); mastitis (1); scarlet fever (1); urinary tract infection (1).